CCL5 (C-C motif chemokine ligand 5)
Diseases named in the same sentence as CCL5 in open-access papers (continued):
Sharing a sentence is not in itself a finding about the gene and the disease.
cancer (continued). "Therefore, some people think that cancer immunotherapy should be combined with a strategy to increas the expression of CCL5 in tumors, thereby enhancing the infiltration of various immune cells into the TME, to increase the therapeutic effect." (PMID 37141250, 2023). "CCL5 is expressed by various cancer cells and plays different roles in shaping TMEs." (PMID 37627528, 2023). "The CXCR4/CXCL12 and CCR5/CCL5 axes, both related to HIV, have been associated with the early (epithelial–mesenchymal transition and invasion) and late events (migration and metastasis) of cancer progression." (PMID 36613922, 2022). "Furthermore, CCL-5 produced by cancer cells in TME recruits monocytes and educates them to have protumoral, immunosuppressive features." (PMID 35208526, 2022). "Mechanistically, we found the UQCRC1/eATP axis reduced the expression of chemokine CCL5 in cancer cells and altered the balance of activating receptor DNAM-1 and inhibitory receptor CD96 on NK-92MI cells, resulting in decreased chemotaxis and exhausted phenotype of NK-92MI cells." (PMID 35769718, 2022). "Another research indicates that immunotherapy combined with blockade of PD-L1 and CCL-5 may provide an effective treatment for patients with pancreatic ductal adenocarcinomas (PDAC) with high cancer Forkhead box protein 3 (Cancer-FOXP3 or C-FOXP3) levels." (PMID 36387070, 2022). "However, the secretion of CCL5 by cancer cells drives the accumulation of immunosuppressive CCR5+ cells and not CD8 T cells in this context." (PMID 36429101, 2022). "In addition to cancer and inflammation, different viral infections, diabetes, Alzheimer’s disease and endometriosis are correlated with the CCL5/CCR5 axis." (PMID 36430633, 2022). "Although chemokine expression in PNETs has been poorly studied, upstream signaling pathways including NF-κB and canonical cyclic GMP-AMP synthase/stimulator of interferon genes (STING) pathways have been shown to regulate CCR5 and CCL5 expression in other types of cancer." (PMID 36301668, 2022). "The CCL5/CCR5 interaction facilitates cancer progression through several different mechanisms." (PMID 36430633, 2022). "CCL5 is known to chemoattract cells and enhance the invasive ability of cancer cells." (PMID 36430633, 2022). "Studies have also associated excess adiposity and high blood glucose levels to Basal-Like Immune Activated subtype of TNBC along with inflammatory and immunity-related factors such as CCL5 which explain poor cancer prognosis in metabolically unbalanced individuals." (PMID 36077676, 2022). "The role of CCL5 in cancer is complicated; it has both protumour and antitumour properties." (PMID 35365161, 2022). "Cancer cells can inhibit CCL5 expression because it attracted CD8+T cells." (PMID 35145917, 2022). "An elevated level of CCL5 in various cancer patients indicates a poor prognosis." (PMID 35327361, 2022). "As expected, NF-κB pathway was activated along with an increased expression of CCL5 after the administration of tucidinostat treatment in CT26 cancer cell lines, and this upregulation of CCL5 expression was abrogated upon pharmacological NF-κB inhibition using BAY11-7082." (PMID 36352411, 2022). "CCL5 represents an efficacious therapeutic target to prevent cancer recurrence and metastasis." (PMID 35327361, 2022). "Moreover, the use of romidepsin, an HDAC inhibitor, or celecoxib, a COX2 inhibitor, reinforces the expression of chemokines such as CXCL9/10 or CCL5 in cancer cells, macrophages and T cells." (PMID 36429101, 2022). "Recently, CCL5 antagonists were shown to be useful in clinical cancer immunotherapy." (PMID 35327361, 2022). "In addition, correlative studies in clinical trials can mechanistically explore the role of eosinophils in cancer immunotherapy by measuring baseline and on-treatment chemokines, such as CCL5/CXCL9/CXCL10/CCL11." (PMID 35954493, 2022).
cancer (continued). "Furthermore, neutralization of CCL5 blunted PARPi-driven fibroblast activation and boosted the cancer suppression efficiency of PARPis in BRCA1/2-wild type and BRCA1/2-mutant OC xenograft models." (PMID 34108603, 2021). "High-level CCL5 expression reportedly enhances regulatory T cell (Treg) cytotoxicity against CD8+ T cells, preemptively causing CD8+ T cell apoptosis that prevents the targeting and clearance of cancer cells." (PMID 34399621, 2021). "In contrast, the expression of genes regulating immune cell trafficking (e.g., CXCL13, CXCL9, XCL2, CCL5), T-cell activation and clonal expansion (e.g., CD27, CD28, ICOS, IL21, IL2) were massively decreased in 9p21-loss tumors across multiple cancer types/subtypes." (PMID 34556668, 2021). "The secretion of pro-stemness paracrine factors such as insulin-like growth factors, inflammatory cytokines (IL-6 and IL-8), and chemokines (CCL2 and CCL5) promotes the conversion of cancer cells into cancer stem cells and reinforce the stemness of existing cancer stem cells." (PMID 34094963, 2021). "Moreover, chemokine expression of CCL5 was increased in cancer specimens and macrophages; especially in macrophages, chemokine expression of CCL5 was significantly lower compared to PIC alone." (PMID 33809574, 2021). "Given CCL5’s role as an immune and cancer cell survival factor, we hypothesized that CCL5 secreted by ZIKV-infected hBMECs could similarly promote prosurvival CCR3/CCR5 signaling responses that permit ZIKV to persistently infect hBMECs." (PMID 34399621, 2021). "This suggests that the concomitant activation of the CCL5/CCR5 axis in the context of Flt3L-based immunotherapy may enhance antitumor immunity in patients with cancer, and this could be potentiated by DNGR-1 blockade." (PMID 33980589, 2021). "CCL5 is highly expressed in cancer where it contributes to inflammation and malignant progression." (PMID 34122426, 2021). "The inhibition of CCL5 secretion by cancer cells or by the TME may represent an additional avenue to counteract liver tumour progression." (PMID 34638423, 2021). "Moreover, PTP1B dephosphorylates the signal transducer and activator of transcription 3 (STAT3), which in turn increases C-C motif chemokine ligand 5 (CCL5) expression responsible for the invasion of cancer cells." (PMID 34638706, 2021). "It suggests that SAA1, CXCL10, CCR5, CCL19, CXCL11, CXCL13, and CCL5 have important function in immunotherapy for cancer patients, and may be used as key regulator genes of immunotherapy." (PMID 34093667, 2021). "Furthermore, CCR5/CCL5 signaling is known to drive tumor heterogeneity, the formation of cancer stem cells and therefore promotes cancer invasion and metastasis in vitro." (PMID 34203660, 2021). "The CCR5/CCL5 axis, apart from having a similar immunomodulatory role to CCR2/CCL2, has also been implicated in cancer progression and metastasis as well as a marker of poor prognosis in several cancers." (PMID 33546207, 2021). "CCL5 is another chemokine that we identified as positively associated with the immune response when bound to different receptors (SDC4, SDC1, and CXCR3 for 16, 15, and 13 cancer types, respectively)." (PMID 34430923, 2021). "The CCR5/CCL5 interaction is involved in the metastasis of various cancer cells." (PMID 32260550, 2020). "In human cancers, intra-tumoral CCL5, XCL1, and XCL2 transcripts closely correlate with NK cells/cDC1 gene signatures and are associated with increased overall patient survival in several cancer types." (PMID 32218226, 2020). "Therefore, host CCL5 can obviously work as an anticancer molecule to mount relevant immune responses against some cancer cells." (PMID 32218434, 2020). "Other studies reported that some cancer cells could repress their own CCL5 expression to hinder migration of anticancer immune cells toward cancer sites." (PMID 32218434, 2020). "The CCL5/CCR5 axis is involved in immunosuppressive TAM polarization in cancer tissues." (PMID 32630699, 2020).
cancer (continued). "Emodin, a natural anthraquinone derivative with tyrosine kinase inhibitory activity, was found to up-regulate the expression of E-cadherin and inhibit the expression of vimentin, β-catenin, and snail by decreasing the expression of CCL5 in adipose tissue of cancer patients." (PMID 32630699, 2020). "For example, evidence from our studies indicated that co-culturing of TNBC cells with mesenchymal stromal cells (MSCs) or cancer-associated fibroblasts (CAFs) in the presence of TNFα or IL-1β stimulation has given rise to contact-dependent increase in CXCL8, CCL2 and CCL5 levels in the co-cultures." (PMID 32605277, 2020). "Thus, cancer-derived CCL5 are generally utilized to evade host’s antitumor responses, representing a procancer role of cancer-secreted CCL5." (PMID 32218434, 2020). "However, in cancer microenvironments in which other types of immune cells, such as DCs and Tregs, are present, it is possible that CCL5 secreted from those cells also affects the functional status of Trm T and NK cells, in addition to autocrine signaling." (PMID 32218434, 2020). "This review summarizes current knowledge on the role of the CCL5/CCR5 axis in cancer." (PMID 32630699, 2020). "CCL5 acts on cancer cells by increasing their proliferation." (PMID 33076281, 2020). "Altogether, these data demonstrate that cGAS–STING signaling in MSCs are activated by IR and drives the production of CCL5, which can remodel the lung microenvironment via recruiting macrophages that are essential for the colonization of cancer cells in the lung." (PMID 32382015, 2020). "In this scenario, reduction of CCL5 levels in the cancer microenvironments of Ccl5ΔPE/ΔPE mice might restrict the availability of rejuvenating CCL5 to cancer cells." (PMID 32218434, 2020). "Finally, it discusses clinical trials of strategies to counteract the CCL5/CCR5 axis in different cancers using maraviroc or therapeutic monoclonal antibodies." (PMID 32630699, 2020). "Similarly, CCL5 was demonstrated as a bad prognostic marker for survival of patients with various types of cancer." (PMID 32545571, 2020). "Importantly, CCL5 was identified in several cancers as a useful biomarker for predicting treatment response and disease progression." (PMID 31955503, 2020). "In addition to its roles in the regulation of inflammatory diseases and the maintenance of local immune cells, CCL5 expressed by cancer cells plays diverse roles in shaping cancer microenvironments toward their own survival." (PMID 32218434, 2020). "On the other hand, CCL5 has also several pro-cancer properties." (PMID 33076281, 2020). "Interestingly, CCL5 is involved in cancer cell proliferation, metastasis and the formation of an immunosuppressive microenvironment." (PMID 31215484, 2019). "Indeed, human breast cancer cells mixed with bone marrow-derived human MSCs, injected subcutaneously, in a mouse model recruit murine MSCs and the further circulating human cancer cells, also stimulating the de novo secretion of the chemokine CCL5." (PMID 31511776, 2019). "Furthermore, it is now widely established that cancer cells with DDR deficiency exhibit constitutive activation of cellular IFN responses and secretion of TIL recruiting chemokines, CCL5 and CXCL10." (PMID 31174611, 2019). "CCL2 and CCL5 also promote cancer cell growth, survival, migration and EMT." (PMID 31484464, 2019). "The CCL5 levels in serum before cancer treatment were correlated with patients' CCL5 genotypes." (PMID 31921621, 2019). "The Bittner breast dataset showed CCL5 elevated in ductal (fold change of 1.4, p = 0.02) carcinoma." (PMID 30850664, 2019). "Thus, both RANTES/CCL5 and IL-6 are molecules that were upregulated upon dsRNA transfection of cancer cells at the protein level as determined by two complementary methods." (PMID 30613350, 2018). "The CCL5/CCR5 axis is a potential therapeutic target in different cancer types." (PMID 29772686, 2018).
cancer (continued). "In addition, its expression on cancer cells, along with CCL5 has found to play an important role in cancer progression and metastasis." (PMID 29358632, 2018). "Similarly, in human cancers, intratumoral CCL5, XCL1, and XCL2 transcripts closely correlate with gene signatures of both NK cells and cDC1 and are associated with increased overall patient survival." (PMID 29429633, 2018). "We observed that the CCL5 inhibition could create a slight, however, insignificant difference in the proliferation rate of cancer cells." (PMID 30224826, 2018). "The five EV-dependent regulated genes whose expression changes were prevented by importazole (i.e. ghrelin, IL-26, IL-17B, Casp1 and CCL5) may be relevant for the pro-tumorigenic activity of cancer EVs." (PMID 28129640, 2017). "In estrogen receptor positive MCF-7 cell lines, CCL5 could increase the number of cancer stem cells in the tumor." (PMID 28693495, 2017). "Moreover, the CCL5/receptor axis has been described to display several effects in cancer, including the recruitment of immunosuppressive cells like Tregs and monocytes." (PMID 28702457, 2017). "Blockingβ-catenin pathway significantly decreases the TNF-α-primed-conditioned medium or CCL5-mediated cancer cell progression by decreasing the enhancement of Slug, suggesting that the CCL5/β-catenin/Slug pathway plays a critical role in hMSC-mediated cancer progression." (PMID 28542126, 2017). "CCL5 may have effects on cancer cell proliferation, metastasis, and the formation of an immunosuppressive microenvironment; it may be a potential therapeutic target in several cancer diseases." (PMID 29088737, 2017). "Results from a heterotopic mouse model of PDAC using nonmetastatic murine Pan02 cancer cells and an orthotopic xenograft mouse model using metastatic human Panc-1 cancer cells revealed that pancreatic cancer expresses CCL5 to recruit CD4+Foxp3+ Treg cells, which have high levels of CCR5." (PMID 29379802, 2017). "Presently, the status of CCL5 in cancer metabolism is unclear." (PMID 29299159, 2017). "Consistent with this, short-term exposure of cancer-associated fibroblasts, mesenchymal stem cells, and osteoblasts to pH 6.8 promotes the expression of inflammatory and nociceptive mediators (NGF, BDNF, IL6, IL8, IL1b and CCL5)." (PMID 28903357, 2017). "Recently, it has also been established that the suppression of cancer cell-produced CCL5 or host CCR5 could result in defective breast tumor vascularization and growth." (PMID 29240722, 2017). "The presence of CCL5-Ab or CCR5-pep did not reduce CM-induced expression of IGF-1, suggesting that adipocyte-released factors different from CCL5 may control IGF-1 production by cancer cells." (PMID 27027351, 2016). "CCL5 is widely established as an inflammatory chemokine secreted by many cell types including activated T cell, macrophage, endothelial cell, stromal cells and cancer cells." (PMID 27166194, 2016). "Our study provides candidates, like CCL5 and macrophages, for cancer therapy." (PMID 26790618, 2016). "Consistently, a negative association of CCL5 staining in TNBC-associated adipose tissue with overall survival is suggestive of a more aggressive cancer behavior." (PMID 27027351, 2016). "Interestingly, we’ve demonstrated that RT rapidly, and with varying kinetics, increases the production of CCL2 and CCL5 across several different murine and human cancer cell lines in vitro." (PMID 27852031, 2016). "In addition to functioning as macrophage chemotactic factor, the secreted CCL5 can also act in an autocrine manner to enhance the invasive capacity of cancer cells." (PMID 26375811, 2015). "Our present results showed that CCL5 produced by ovarian CSLCs could promote cancer cell metastasis by inducing EMT." (PMID 25788271, 2015).
cancer (continued). "To further assess the contribution of CCL5 expressed by BMDCs on metastatic phenotype, we asked whether CCL5 expressed by BMDCs is sufficient or necessary for the invasive properties of cancer cells." (PMID 26497998, 2015). "Different groups have also identified osteopontin, Insulin-like-Growth Factor-1 (IGF-1) or the pro-inflammatory peptide LL-37 as possible secreted factors by cancer cells, which could increase CCL5 levels in MSCs." (PMID 26362269, 2015). "We note that our previous study associated CCL5 protein expression in the lungs and lymph nodes with metastatic potential, but not normal LECs or cancer cells." (PMID 26173622, 2015). "In an attempt to examine the role of CCL5 in cancer metastasis, Dr. Zhu and colleagues employed several complementary approaches to test the hypothesis that cancer stem cell-derived CCL5 played a role in endowing CSCs with invasive properties." (PMID 26328269, 2015). "While we also found HIF1α could be induced after recruited BM-MSCs (with increased CCL5) in PCa cells, we focused on HIF2α here as the recent studies showed that the HIF2α is more important for the cancer stem cell population induction." (PMID 26342197, 2015). "For cancer cells to respond to CCL5, they should express its receptor (CCR5)." (PMID 26497998, 2015). "Alternatively, chemotherapy drugs could affect both proliferation and the formation of an immunosuppressive microenvironment by decreasing the secretion of CCL5 by cancer cells, as reported for the PI3Kδ-specific inhibitor GS-1101 in cHL cells." (PMID 24523569, 2014). "Among them, the cancer invasion-related factor CCL5 was quantified by ELISA." (PMID 25271422, 2014). "Previous studies reported CCL5 promoting cancer migration by PI3K-dependent Akt activation." (PMID 25301739, 2014). "The interaction of CCL5 with its receptor CCR5 promotes cancer cell migration under hypoxia." (PMID 24265713, 2013). "Previous studies have shown that CCL5 modulates cell migration and invasion in human cancer cells." (PMID 22506069, 2012). "Indeed, we found that miR-146a over-expression reduced expression of several cytokines and growth factors with a known role in cancer development; IL-8, IL-23A, CCL5, CSF-1 and PDGFB." (PMID 22992343, 2012). "CCL5 has been reported to stimulate directional migration and invasion of human cancer cells." (PMID 22506069, 2012). "Thus, in cancer, various cytokines, including IL-6 and CCL5, are secreted into the TME at various stages of inflammation, and their complex interactions and secretions may be altered." (PMID 39126553, 2024). "The study demonstrated how co-culturing BCa cells with human adipocytes heightened the invasiveness of cancer cells through increased secretion of CCL5, suggesting that inhibiting CCL5 in the adipose microenvironment could be a promising strategy to curb highly malignant TNBC." (PMID 39040042, 2024). "In addition, CCL5 treatment also produced larger size and quantity of cancer stem cells." (PMID 36836690, 2023). "Genotypes in the CCL5/CCR5 gene can identify specific populations that would benefit from bevacizumab (BEV: the first anti-angiogenic agent targeting VEGF-A that has been widely used in a variety of cancer types, including mCRC) in the first-line treatment of patients with mCRC." (PMID 36387070, 2022). "Their findings showed that crosstalk between MSCs and cancer cells can be attributed to CD9, the overexpression of which is associated with a higher risk of invasion and metastasis as well as the promotion of the expression of BCRP and MDR1, which is mediated via CCL5, CCR5 and CXCR12." (PMID 35954425, 2022). "We have chosen to focus our functional assays on CCL5 in part because of the availability of Maraviroc as an FDA-approved HIV therapeutic that we would propose may have the potential to be repurposed for cancer treatment." (PMID 33868996, 2021). "However, negligible induction of CCL5 expression in cancer cells was observed." (PMID 34108603, 2021).